NOX4 (NADPH oxidase 4)
Diseases named in the same sentence as NOX4 in open-access papers (continued):
Sharing a sentence is not in itself a finding about the gene and the disease.
non-small cell lung carcinoma (22 papers, 2014 to 2025). A group of at least three distinct histological types of lung cancer, including non-small cell squamous cell carcinoma, adenocarcinoma, and large cell carcinoma. "NOX4 recruited M2-type tumor-associated macrophages to promote tumor growth via regulating ROS/PI3K axis in non-small-cell lung cancer." (PMID 35154560, 2022). "A study on non-small cell lung cancer (NSCLC) cells revealed that abundantly expressed NOX4 in NSCLC cells contributed to the cancer progression through activation of the ROS/PI3K pathway." (PMID 41071399, 2025). "NOX4 directs glucose metabolism not only toward glycolysis but also to PPP for the production of NADPH in non-small cell lung cancer (NSCLC) cells." (PMID 36768405, 2023). "In non-small cell lung cancer, NOX4 induces glycolysis through the ROS/PI3K/AKT pathway, and the NOX4 inhibitor in combination with a glycolysis inhibitor exert a synergistic inhibitory effect on cancer cells." (PMID 37670970, 2023). "Through the recruitment of M2 TAM through the generation of different cytokines in response to ROS/PI3K signaling, tumor NOX4 stimulates the proliferation of non-small cell lung cancer cells." (PMID 36159818, 2022). "For example, NOX4 was found to function as an oncogene in non-small-cell lung cancer by enhancing glycolysis." (PMID 35154560, 2022). "In non-small-cell lung cancer cells, NOX4 and NOX4-generated ROS promote glycolysis and modify glutamine metabolism." (PMID 34257808, 2021). "In non-small cell lung cancer, Nox4 expression is positively correlated with IL-6 expression and exogenous IL-6 treatment significantly enhances Nox4 signaling." (PMID 30513726, 2018). "Zhang and coworkers found that NOX4 was up-regulated in non small cell lung cancer, and promoted its growth and metastasis." (PMID 26330360, 2015). "Reports have suggested that NOX4 may be a potential therapeutic target against both non-small cell lung cancer and tuberculous fibrosis." (PMID 33567693, 2021). "Furthermore, the inflammatory cytokine IL-6 has been found to produce ROS through increased expression of NADPH oxidase 4 (NOX4) in non-small cell lung cancer." (PMID 26881031, 2016). "However, what the role of NOX4 plays during malignant progression of non-small cell lung cancer (NSCLC) remains unknown." (PMID 24946933, 2014). "NOX4 interacts with IL-6/STAT3 and PI3K/Akt signaling pathways to promote non-small-cell lung carcinoma cell proliferation and survival." (PMID 36874093, 2023). "In non-small cell lung cancer, NADPH oxidase 4 (NOX4) expression is increased, which can activate the PI3K/Akt signaling pathway through ROS increase." (PMID 37369681, 2023). "In non-small cell lung cancer, oncogenic alterations in the epidermal growth factor receptor (EGFR) increase cellular sensitivity to ferroptosis, due to mitogen-activated protein kinase (MAPK) signaling-mediated NADPH oxidase 4 (NOX4) activation." (PMID 36282248, 2022). "NOX4 is also highly expressed in non-small cell lung cancer (NSCLC) and promotes cancer progression by inducing glycolysis during c-Myc activation via the ROS/PI3K/Akt pathway, while GKT137831, a selective NOX4 inhibitor, suppresses the growth of tumor cells both in vitro and in vivo." (PMID 34885171, 2021).
prostate carcinoma (22 papers, 2014 to 2025). A carcinoma that arises from epithelial cells of the prostate gland. "Increased Nox4 gene expression has also been reported in prostate cancer-associated stroma." (PMID 35836253, 2022). "In human prostate cancer, NOX4 mediates TGFβ1-induced activation of primary fibroblasts to acquire a CAF-associated phenotype." (PMID 35646942, 2022). "Silibinin, an active compound of milk thistle, induces ER stress and apoptosis by upregulating Nox4 and ROS release in prostate cancer cells." (PMID 34830138, 2021). "NOX4 overexpression has also been found in diverse types of solid tumors, such as prostate cancer, liver cancer, CRC, and melanoma 18-22." (PMID 32641980, 2020). "Here we have investigated NOX2 and NOX4 gene expression in prostate cancer microarray databases and evaluated their gene expression in fresh-frozen tissue sections from radical prostatectomies." (PMID 30459931, 2018). "This study demonstrates the functional relevance of elevated expression of Nox4—which is a major source of cellular reactive oxygen species (ROS)—in the tumor microenvironment and downstream consequences on prostate cancer (PCa)‐relevant processes." (PMID 29441570, 2018). "In addition, NOX4 mRNA levels in prostate cancer are significantly higher than those in benign prostate tissues." (PMID 29065504, 2017). "Therefore, the regulation of NOX4, mitochondrial ROS producer, could be a potential target for the treatment of prostate cancer." (PMID 27405931, 2016). "Preradiation treatment of human prostate cancer cells with Nox inhibitors sensitized the cells to radiation similar to androgen deprivation therapy, further supporting the notion that enhanced Nox4 levels are protective against radiation-induced tumor cell death." (PMID 24868315, 2014). "Our results indicated that Apl-1 treatment activated the protein expression of NOX4 and NOX2 in prostate cancer cells PC-3 and Du145, respectively." (PMID 35629355, 2022). "The opposite result was observed for stem-like holoclones derived from the PC3 human prostate cancer cell line, which showed reduced expression of NOX2, NOX4, and NOX5, and their upregulation significantly lowered cell survival in vitro." (PMID 28626501, 2017). "Collectively, these findings indicate that TREX1, NOX4, and RRM2 may be significant contributors to the progression of prostate cancer; however, their precise roles and potential therapeutic implications warrant further investigation." (PMID 41346575, 2025). "This difference may account for the increased tumour formation in the prostates of the A537T‐TRAMP, where semaphorins and Nox4 were increased, compared with the KO‐TRAMP mice, as these proteins can contribute to more invasive prostate cancer." (PMID 37093546, 2023). "NOX4 is highly expressed in prostate cancer cell lines and in prostate cancer tissues compared with normal prostate cell lines or benign prostate tissues, respectively." (PMID 29478325, 2019). "In addition to androgens, adiponectin has induced a strong increase in NOX2 and NOX4 mRNA expression in DU145 and 22Rv1 human prostate cancer cells, which were NOX2-dominated and NOX4-dominated, respectively." (PMID 29065504, 2017). "We have identified several malignant histologies (esophageal, head and neck, and prostate carcinomas) that have not previously been reported to show substantial NOX4 expression by IHC." (PMID 28578276, 2017). "Interestingly, in rat prostate cancer, castration results in dramatic increases in NOX1, NOX2, and NOX4." (PMID 29065504, 2017). "In addition, studies have reported that various isoforms of NOX are found in prostate cancer cell lines, including NOX4, NOX2, and NOX5, which are absent in normal prostate cell lines." (PMID 34336107, 2021). "Thus, NOX1, NOX2, NOX4, and NOX5 may be potential targets for therapeutic intervention in prostate cancer." (PMID 34336107, 2021).
prostate carcinoma (continued). "In the present study we have revealed from the human microarray databases that NOX4 expression is elevated in prostate cancer compared to normal tissue, however, from the Tomlins review it appears that NOX4 is elevated predominantly in metastatic prostate cancer and not in primary prostate cancer." (PMID 30459931, 2018).
renal cell carcinoma (22 papers, 2012 to 2025). "Moreover, both ROS generation and NOX4 expression are essential for HIF-2α transcriptional activity in VHL-deficient renal cell carcinoma, indicating that higher levels of ROS can contribute to HIF-2α stabilization and are key to facilitate and sustain the aggressive phenotype of cancer cells." (PMID 33540838, 2021). "In von Hippel Lindau (VHL)-deficient renal cell carcinoma (RCC), NOX4 also promotes renal tumorigenesis in a similar signal pathway via nuclear accumulation of HIF-2α, not HIF-1α." (PMID 28594389, 2017). "For example, hypoxia-induced IL-6 and IL-8 promote renal cell carcinoma cell invasion, which is dependent on NOX4 expression." (PMID 32641980, 2020). "As a previous study indicates that NOX4 mediates hypoxia-induced IL-6 production in renal cell carcinoma cells, we next sought to the possible correlation of NOX4 and IL-6 expression levels in NSCLC." (PMID 25504436, 2015). "A previous study indicates that NOX4 mediates production of various pro-inflammatory cytokines including IL-6 in renal cell carcinoma cells." (PMID 25504436, 2015). "In contrast, the ferroptosis of renal cell carcinoma is mediated by renal-specific NOX4." (PMID 33062192, 2020). "Besides, NOX4 has been also shown to promote renal cell carcinoma cell invasion through hypoxia-induced interleukin 6-and 8-production." (PMID 24946933, 2014). "Besides, NOX4 is also involved in renal cell carcinoma cell invasion and metastasis through hypoxia-induced interleukin 6- and 8- production." (PMID 24946933, 2014). "Our laboratory and others has identified Nox oxidases, and particularly the isoform Nox4, as a major source of ROS in renal cell carcinoma and our group has previously demonstrated that AMP-activated protein kinase (AMPK) is a novel upstream regulator of Nox oxidase protein expression and activity." (PMID 22303451, 2012). "Furthermore, NOX4 is shown to increase IL-6 and IL-8 production in renal cell carcinoma." (PMID 28099519, 2017). "TAZ induces ferroptosis in renal cell carcinoma by upregulating epithelial membrane protein 1 (EMP1) expression, which promotes NADPH oxidase 4 (NOX4)." (PMID 40619484, 2025). "As shown in a study on renal cell carcinoma (RCC), NOX4 is an ATP‐binding motif within the NADPH‐oxidized isoform and located in the inner membrane of mitochondria." (PMID 38151790, 2023). "In renal cell carcinoma (RCC), an NADPH oxidase isoform, NOX4, localizes to the inner mitochondrial membrane, and subcellular redistribution of ATP levels from the mitochondria activates NOX4." (PMID 30410721, 2018). "NOX may be linked to inflammation-induced metastasis in renal cell carcinoma (RCC), where cell invasion is based on NOX4-mediated hypoxic-induced production of interleukin-6 and interleukin-8 (IL-6 and IL-8)." (PMID 28626501, 2017). "In a model of renal cell carcinoma, the molecular mechanism for ferroptosis resistance in highly confluent cells involved TAZ-induced regulation of epithelial membrane protein 1 (EMP-1) and NADPH oxidase 4 (NOX4)." (PMID 35065965, 2022).
Alzheimer disease (21 papers, 2019 to 2026). A progressive, neurodegenerative disease characterized by loss of function and death of nerve cells in several areas of the brain leading to loss of cognitive function such as memory and language. "We found, through microarray analysis, that stimulation of microglia cells with P. gingivalis resulted in the upregulation of several Alzheimer’s disease-associated genes, including NOX4." (PMID 39469453, 2024). "Although NOX4 has been repeatedly implicated in the progression of Alzheimer’s disease and Parkinson’s disease, its upregulation occurs primaily in astrocytes." (PMID 39499702, 2024). "Out of the genes associated with Alzheimer’s disease, NOX4, a primary enzyme responsible for the production of ROS, was found to be of special interest for further evaluation." (PMID 39469453, 2024). "When evaluating the genes associated with Alzheimer’s disease, NOX4, which was upregulated, was found to be of particular interest." (PMID 39469453, 2024). "Our findings, coupled with existing research, position NOX4 as a central mediator of PM-induced ROS production, particularly given its mitochondrial localization and potential role in ferroptosis, a process linked to mitochondrial metabolism impairment in Alzheimer’s disease." (PMID 38892302, 2024). "Avicularin, a flavonoid component of Z. bungeanum peel, can inhibit ferroptosis and improve cognitive impairment in Alzheimer’s disease by regulating the NOX4/Nrf2 axis." (PMID 40093316, 2025). "Current research highlights NOX4’s potential significance in neurodegenerative diseases, including Parkinson’s and Alzheimer’s diseases." (PMID 38956702, 2024). "This study investigates NADPH oxidase 4 (NOX4) involvement in iron-mediated astrocyte cell death in Alzheimer’s Disease (AD) using single-cell sequencing data and transcriptomes." (PMID 38956702, 2024). "Our findings have unveiled a potential relationship between NOX4 and iron-induced cell death in Alzheimer’s disease, offering a novel insight into unraveling the intricate pathogenesis of Alzheimer’s." (PMID 38956702, 2024). "To investigate the role of NOX4 in Alzheimer’s disease, we conducted immunofluorescence staining to measure the levels of NOX4 protein in GFAP-positive astrocytes in the cortical region of APP/PS1 transgenic mice and wild-type (WT) mice." (PMID 38956702, 2024). "The relationship between NOX4 and iron death in astrocytes in Alzheimer’s disease (AD) is currently unclear." (PMID 38956702, 2024). "This study’s primary objective is to elucidate the critical role of NADPH oxidase 4 (NOX4) in iron-triggered astrocytic cell death and its implications for Alzheimer’s disease (AD) pathogenesis." (PMID 38956702, 2024). "Research shows that NOX4 promotes ferroptosis of astrocytes by lipid peroxidation induced by mitochondrial metabolic damage in Alzheimer’s disease (AD)." (PMID 36911415, 2023). "In an Alzheimer’s disease study, ferroptosis was shown to occur in astrocytes and is positively regulated by NADPH oxidase 4-mediated impairment of mitochondrial metabolism." (PMID 36713782, 2022). "NOX4 promotes ferroptosis in astrocytes through lipid peroxidation induced by oxidative stress by impairing mitochondrial metabolism in Alzheimer’s disease." (PMID 36389694, 2022). "One strength of this study lies in the precise identification of the differential gene NOX4 in Alzheimer’s disease patients using single-cell sequencing technology, linking astrocytes with iron-induced cell death and offering a new perspective on the complex pathogenesis of Alzheimer’s disease." (PMID 38956702, 2024). "The expression level of NOX4 is increased in patients with Alzheimer’s disease and animal models." (PMID 38956702, 2024). "Subsequent experiments could investigate the impact of TNFα regulation on NOX4 in astrocytes, exploring its influence on iron-induced cell death and its role in Alzheimer’s disease." (PMID 38956702, 2024).
Alzheimer disease (continued). "Further research and exploration into the role of NOX4 may help uncover the pathogenesis of Alzheimer’s disease and provide potential therapeutic strategies." (PMID 38956702, 2024). "In addition, NOX4 expression is also upregulated in patients with Alzheimer’s disease or frontotemporal dementia, questioning the role of NOX4 in neurodegeneration." (PMID 37081190, 2023). "Furthermore, the involvement of ferroptosis in conditions like Alzheimer's disease has been highlighted, with nicotinamide adenine dinucleotide phosphate oxidase 4 (NOX4) contributing to the ferroptosis of astrocytes through the induction of lipid peroxidation mediated by oxidative stress." (PMID 39724413, 2024). "For example, in Alzheimer's disease, NADPH oxidase 4 (NOX4) induces ferroptosis in astrocytes by promoting oxidative stress-induced lipid peroxidation via the impairment of mitochondrial metabolism." (PMID 39918890, 2025). "To investigate the potential of silencing NOX4 in mitigating iron-induced cell death and alleviating Alzheimer’s disease, we conducted experiments on APP/PS1 transgenic mice by employing NOX4 knockdown and erastin treatment." (PMID 38956702, 2024). "For instance, in Alzheimer’s disease, NADPH Oxidase 4 (NOX4) promotes ferroptosis in astrocytes by inducing oxidative stress-induced lipid peroxidation and impairing mitochondrial metabolism." (PMID 38155662, 2023). "Decreased Fpn expression and abnormal iron deposition significantly increased NOX4, 4-HNE, and MDA levels in damaged astrocytes of cerebral cortex, and five hub genes (JUN, SLC2A1, TFRC, ALB, and NFE2L2) closely related to ferroptosis were identified in Alzheimer's disease (AD) patients." (PMID 36062196, 2022).